FAM47E (family with sequence similarity 47 member E)
Description:
Promotes histone methylation by localizing the arginine methyltransferase PRMT5 to chromatin.
Synonyms: FLJ42946; LOC100129583
Tractability: No criterion of Open Targets' tractability assessment is met for any kind of drug.
Gene: Protein-coding gene on chromosome 4 (76,214,040 to 76,284,294, forward strand). Ensembl gene ENSG00000189157.
Subcellular location: Nucleus; Chromosome; Cytoplasm
Subcellular location (Human Protein Atlas): Cytosol; Plasma membrane; Nucleoplasm
Gene Ontology:
Molecular function: enzyme activator activity; protein binding
Biological process: protein localization to chromatin; transcription initiation-coupled chromatin remodeling
Cellular component: chromatin; chromosome; cytoplasm; cytosol; nucleoplasm; nucleus
Genetic constraint (gnomAD): Loss-of-function variants: 30 observed, 34.72 expected, observed/expected ratio (o/e) 0.86, 90% interval 0.65 to 1.17. The upper end of that interval is the gene's LOEUF score, 1.17, which puts it in group 5 of 6, group 1 being the genes least tolerant of losing a copy. Missense variants: 374 observed, 411.25 expected, observed/expected ratio (o/e) 0.91, 90% interval 0.83 to 0.99. Synonymous variants: 165 observed, 162.23 expected, observed/expected ratio (o/e) 1.02, 90% interval 0.89 to 1.16.
Homologues: Orthologues: chimpanzee FAM47E (97% identical), macaque FAM47E (82% identical), pig FAM47E (56% identical), mouse Fam47e (51% identical), rat Fam47e (50% identical), tropical clawed frog fam47e (31% identical), zebrafish zgc:158260 (20% identical), Drosophila melanogaster tau (18% identical), Caenorhabditis elegans nfyb-1 (6% identical), Drosophila melanogaster Nf-YB (6% identical). Paralogues in human: NFYB (8% identical), DR1 (6% identical).
Diseases named in the same sentence as FAM47E in open-access papers:
FAM47E is named in the same sentence as 5 diseases in open-access papers, as found by Europe PMC text mining. Sharing a sentence is not in itself a finding about the gene and the disease. The quoted sentences say what the papers report.
Parkinson disease (3 papers, 2021 to 2023). A progressive degenerative disorder of the central nervous system characterized by loss of dopamine producing neurons in the substantia nigra and the presence of Lewy bodies in the substantia nigra and locus coeruleus. "The family with sequence similarity 47 member E (Fam47e) gene, linked to myoclonic epilepsy and Parkinson’s disease, showed a notable upregulation of 2.2-fold." (PMID 38283372, 2023). "Genome wide association studies indicated that the FAM47E is associated with chronic kidney disease and Parkinson’s disease." (PMID 33376131, 2021). "Previously, the SCARB2/FAM47E locus has also been implicated with Parkinson disease (PD)." (PMID 34935119, 2022).
chronic kidney disease (2 papers, 2021 to 2024). Impairment of the renal function secondary to chronic kidney damage persisting for three or more months. "The FAM47E gene has been linked to chronic kidney disease and PD, according to genome-wide association studies." (PMID 38421723, 2024).
esophageal cancer (1 paper, 2021). A primary or metastatic malignant neoplasm involving the esophagus. "Interestingly, in conditions, especially in esophageal cancer, where PRMT5 is not up-regulated but FAM47E was significantly up-regulated, substantial proportion of targets positively regulated by PRMT5 were also significantly up-regulated." (PMID 33376131, 2021).
FAM47E also shares sentences with these, for which no sentence is quoted: myoclonic epilepsy (1 paper); tumor (1).